SALL4 (spalt like transcription factor 4)
Diseases named in the same sentence as SALL4 in open-access papers (continued):
Sharing a sentence is not in itself a finding about the gene and the disease.
germ cell tumor (37 papers, 2011 to 2025). A benign or malignant, gonadal or extragonadal neoplasm that originates from germ cells. "Based on these results, SALL4 is introduced as a novel sensitive and specific marker for metastatic germ cell tumors and as a novel diagnostic marker for metastatic yolk sac tumors from the testis, ovary, and extragonadal sites." (PMID 23363002, 2013). "As a novel known diagnostic marker for primary germ cell tumors, SALL4 was also examined in comparison with KPNA2." (PMID 22962582, 2012). "SALL4 is also identified as a novel sensitive diagnostic marker for primary germ cell tumors of the central nervous system with high specificity, and is a more sensitive marker than α-fetoprotein and glypican-3 for yolk sac tumors." (PMID 22962582, 2012). "In some cases, particularly in non-germ cell tumors, SALL4 may be present on its own, which may also have diagnostic value." (PMID 41373846, 2025). "In our case, the tumor exhibited positivity for CD117 and SALL4 while demonstrating negativity for other germ cell tumor markers." (PMID 40832615, 2025). "SALL-4 is a germ cell marker that is typically positive in dysgerminoma and is usually used to differentiate germ cell tumors from epithelial neoplasms." (PMID 41510478, 2025). "Initial biopsy findings suggested a germ cell tumor based on immunoreactivity for markers such as SALL-4 and cytokeratin." (PMID 40225550, 2025). "Depending on the age of the patient, germ cell tumors can also come into differential diagnosis, especially yolk sac tumors, in which case SALL4 negativity favors SLCT, but one has to remember that focal AFP expression is common in SLCT." (PMID 39592485, 2025). "In germ cell tumors, SALL4 is strongly positive in over 90% of cells, whereas in clear cell carcinoma, SALL4 expression is very rare and limited to individual cases." (PMID 41373846, 2025). "The initial biopsy indicated a germ cell tumor with yolk sac based on these immunohistochemical markers: SALL-4, cytokeratin, and vimentin." (PMID 40225550, 2025). "SALL4 has proven highly specific for germ cell tumors, showing only weak staining on some ovarian clear cell tumors and metastatic gastrointestinal adenocarcinomas, without reacting with any granulosa cell, theca cell, or ovarian stromal cell tumors." (PMID 37443818, 2023). "As a sensitive and specific marker of germ cell tumors, SALL4 has been proved to be expressed in immature elements such as primitive neuroepithelial tissue and blastema-like stroma but not in mature tissues." (PMID 36309682, 2022). "In the present case, immature / atypical intestinal glands and neuroepithelium were positive for SALL4, which is known as a sensitive and specific marker of germ cell tumors." (PMID 31684979, 2019). "SALL4 was highly‏ expressed in several solid tumors such as breast cancer,‏ germ cell tumor, hepato and gastric cancers, as‏ well as colon carcinoma." (PMID 28959334, 2016). "Recent studies have‏ shown that SALL4 is an excellent target for assessment‏ of treatment with regard to several types of cancers‏ including, liver, ovarian primitive germ cell, and‏ testicular germ cell tumors." (PMID 28959334, 2016). "Recently, SALL4 has been reported to be positive not only in primitive germ cell tumors but also in somatic malignancies." (PMID 22848863, 2012). "SALL4 belongs to a family of zinc finger transcription factors and is a novel finding stem cell biomarker which has been identified for germ cell tumors of central nervous system and primary mediastinum." (PMID 22962582, 2012). "SALL4 is a sensitive marker for germ cell tumors and is positive in most MOGCT subtypes." (PMID 41018086, 2025). "A comprehensive immunohistochemical study has shown that SALL4 is consistently expressed in all germ cell tumors, whereas in non-germ cell tumors, such as serous ovarian cancer, SALL4 expression occurs in approximately 20% of cases, usually in poorly differentiated forms." (PMID 41373846, 2025).
germ cell tumor (continued). "SALL4 is a novel sensitive and specific marker for both primary and metastatic germ cell tumors." (PMID 34706681, 2021). "Furthermore, with regard to germ cell multipotency, the germ cell-like cells positive for SALL4 – an immunohistochemical marker for germ cell tumors – constituted a part of the tumor." (PMID 32972454, 2020). "The association‏ between SALL4 and OCT4, NANOG, and SOX2 suggests‏ that SALL4 might be a candidate marker for the‏ metastatic germ cell tumors." (PMID 28959334, 2016). "SALL4 is expressed in fetal organs, including fetal livers, diminished gradually during development of the embryo and silenced in most of the adult tissues but re-expressed in some solid tumors, germ cell tumors and leukemia." (PMID 27329034, 2016). "In addition to germ cell tumors, SALL4 has been shown to be expressed in somatic malignancy including lung, breast, leukemia malignant rhabdoid tumor, and Wilm's tumor." (PMID 22848863, 2012). "These cells in the current case were positive for GPC3 and SALL4, which are known as oncofetal proteins expressed in germ cell tumors, contributing to the need of additional immunohistochemical staining for differentiating germ cell tumors from clear cell type EOC in the current case." (PMID 29933751, 2018). "Also, expression of SALL4 was detected in more than 90% of tumor cells of metastatic seminomas, dysgerminomas and embryonal carcinomas suggesting that SALL4 play a role in development of germ cell tumors." (PMID 23363002, 2013). "CT-guided needle biopsy revealed a Schiller-Duval body with a perivascular arrangement and positive immunohistologic staining for Sal-like protein 4 (SALL4), a specific marker for germ cell tumors, leading to a diagnosis of yolk sac tumor." (PMID 39790263, 2024). "A combination of antibodies, including Sal-like transcription factor 4 (SALL4), octamer-binding transcription factor 3/4 (OCT3/4) and α-fetoprotein (AFP), have been used to diagnose germ cell tumors." (PMID 38090508, 2023). "Mediastinal germ cell tumors can generally be distinguished from epithelial neoplasms based on clinical (serological), histological, and immunocytochemical findings, such as positivity for SALL4 and OCT3/4, and other more specific germ cell tumor markers." (PMID 35454918, 2022). "In a study of 3215 tumor metanalyses, SALL4 was consistently expressed in germ cell tumors but only rarely in non-germ cell tumors, supporting its high specificity." (PMID 41373846, 2025). "SALL4 is highly specific for germ cell tumors, with minimal staining in non-germ cell ovarian tumors." (PMID 41373846, 2025). "By combining these markers with non-germ cell tumors markers, such as PLAP and SALL4, it possible to differentiate germ cell tumors from epithelial and gonadal stromal neoplasms in most cases." (PMID 37443818, 2023). "In our case, germ cell tumors including yolk sac and embryonal carcinoma were the most possible differentials which were excluded by the negative IHC results for SALL4, CD30, Glypican 3 and AFP (alpha-fetoprotein)." (PMID 35797874, 2022). "The markers of sex cord tumors (calretinin and inhibin-α) and germ cell tumors (SALL4 and OCT3/4) are negative, while CD10 and β-catenin (nuclear and cytoplasmic) are characteristically positive." (PMID 34044845, 2021). "Excisional biopsy of inguinal lymph nodes revealed poorly differentiated embryonal cell carcinoma with strong expression of SALL4, a rare expression of OCT 3/4, and the absence of expression of CD30 and placental alkaline phosphatase (PLAP)." (PMID 32399369, 2020). "Recently, novel stem cell markers, SALL4, OCT4, NANOG, SOX2, UTF1, and TLC1 have been proposed as novel sensitive diagnostic markers for primary mediastinal germ cell tumors, with high specificity." (PMID 22962582, 2012). "However, the positivity for EMA and CEA, combined with negativity for spalt-like transcription factor 4 (SALL4) - a highly sensitive marker for germ cell tumors - ruled out seminoma definitively." (PMID 40585691, 2025).
germ cell tumor (continued). "Both SALL4 and glypican-3 though considered as marker for germ cell tumor should not be used alone in differentiating MMMT from germ cell tumors." (PMID 22848863, 2012). "Negative SALL4 and OCT3/4 ruled out the possibility of a germ cell tumor, like dysgerminoma." (PMID 39021466, 2024). "In addition, immunohistochemical analysis of AFP, Sal-like protein 4 (SALL4), PLAP, c-kit, and D2-40, performed to differentiate chordoma from lung metastases of germ-cell tumors, were all negative." (PMID 38961474, 2024).
Duane-radial ray syndrome (33 papers, 2009 to 2025). "SALL4 heterozygous mutations can cause Okihiro syndrome, an autosomal dominant inherited disorder called Duane-radial ray syndrome (DRRS, MIM: 607,323)." (PMID 40483479, 2025). "SALL4 pathogenic variants lead to Duane-radial ray syndrome, an autosomal dominant syndrome that presents a pattern of limb anomalies very similar to the ones identified in thalidomide embryopathy." (PMID 37511270, 2023). "In this study, we describe a novel de novo heterozygous nonsense mutation in SALL4 gene segregating with duane radial ray syndrome in an Iranian family." (PMID 36829172, 2023). "Mutations in SALL4 are associated with Okihiro syndrome, and SALL4 is also a known target of thalidomide." (PMID 36635047, 2023). "Sall4 encodes a zinc finger transcription factor, and mutations in human SALL4 cause Duane-radial ray syndrome, an autosomal dominant disorder." (PMID 35482646, 2022). "SALL4 is a transcription factor (TF) involved in limb development; in humans, loss-of-function mutations in SALL4 cause Duane-radial ray syndrome, an autosomal recessive condition characterized by limb anomalies, similar to the ones observed in TE." (PMID 34249098, 2021). "Mutations in SALL4 are associated with Duane-radial ray syndrome/Okihiro syndrome and SALL4-related Holt-Oram syndrome, both of which show phenotypes similar to those of thalidomide embryopathy." (PMID 33777938, 2021). "SALL4 mutations are also associated with developmental syndromes, including Okihiro syndrome, Holt-Oram syndrome, and Townes-Brocks Syndrome50." (PMID 34753942, 2021). "Variants in the SALL4 gene are associated with Duane-radial ray syndrome (OMIM #607323), an autosomal dominant disorder characterized by upper limb, ocular, and renal anomalies." (PMID 32656166, 2020). "As all three family members share a pathogenic variant in SALL4 and present with features of the Duane-radial ray syndrome, this diagnosis seems appropriate." (PMID 32656166, 2020). "Based on the clinical phenotype and the presence of a missense variant in SALL4 that is highly likely to be deleterious, a diagnosis of Duane-radial ray syndrome seems appropriate for this patient." (PMID 32656166, 2020). "For instance, a mutation in SALL1 is linked to the autosomal disease, called Townes-Brocks syndrome, while mutant forms of SALL2 are present in human ovarian carcinoma and a mutation in SALL4 leads to Okihiro syndrome (Duane-radial ray syndrome)." (PMID 32718932, 2020). "It was already known that mutations in the gene that produces SALL4 cause two conditions called Duane Radial Ray syndrome and Holt-Oram syndrome." (PMID 30067223, 2018). "Heterozygous mutations in the human SALL4 gene cause Duane-radial ray syndrome (also known as Okihiro syndrome), an autosomal dominant disorder." (PMID 30401915, 2018). "Mutations in SALL4 result in Okihiro syndrome, characterised by defective heart and kidney development." (PMID 29228922, 2017). "Homozygous loss-of function mutation of SALL4 are lethal for the embryo, while heterozygous mutations cause renal-ocular syndrome and the Okihiro syndrome, associated with multi limbs defects, deficient eye movements, renal malformations, and deafness." (PMID 28160555, 2017). "SALL4 mutation causes Okihiro syndrome and many researchers have demonstrated that SALL4 is essential in hematopoietic stem cells and regulates their expansion." (PMID 24860834, 2014). "Sall4 is also a causative gene for Okihiro syndrome and is essential for the formation of many organs in both humans and mice." (PMID 23825698, 2013). "On the other hand, some patients suffering from Okihiro syndrome, which is caused by SALL4 mutations, exhibit kidney abnormalities." (PMID 23825698, 2013). "Mutations in SALL1 and SALL4 have been associated with Townes-Brocks syndrome and Okihiro syndrome, respectively, which are both autosomal dominant diseases that involve abnormalities in various organs, including the ears, limbs, heart, and kidneys." (PMID 23825698, 2013).
Duane-radial ray syndrome (continued). "To date, 22 SALL4 mutations have been described in Duane-related syndromes, especially Okihiro syndrome." (PMID 23687435, 2013). "In humans, mutations in SALL1 are associated with Townes Brocks Syndrome, while mutations in the SALL4 gene are associated with the Duane-Radial Ray or Okihiro Syndrome." (PMID 22978642, 2012). "In human, SALL4 is mutated in patients with Duane Radial Ray Syndrome (DRRS, OMIM#126800) (also known as Duane Anomaly with Radial Ray abnormalities and Deafness syndrome or Okihiro syndrome) and Acro-renal-ocular syndrome." (PMID 20505821, 2010). "SALL4 mutations also result in a range of overlapping phenotypes, including Holt-Oram and Acro-renal-ocular syndrome, and IVIC syndrome." (PMID 20505821, 2010). "A number of likely pathogenic mutations have been reported for SALL4 in Okihiro syndrome patients." (PMID 36635047, 2023). "SALL4 was selected from the list of proteins degraded upon thalidomide treatment because it was previously identified as the causal gene of hereditary diseases such as Duane Radial Ray syndrome, Okihiro syndrome and Holt–Oram syndrome." (PMID 32414180, 2020). "Strikingly, human genetic research has shown that familial loss of function (LOF) mutations in SALL4 are causatively linked to the clinical syndromes, Duane Radial Ray syndrome (DRRS) also known as Okihiro syndrome, and mutated in some patients with Holt-Oram syndrome (HOS)." (PMID 30067223, 2018). "Interestingly, in humans the Duane-Radial Ray Syndrome is caused by the deletion of one copy of SALL4, suggesting that also in humans two copies of a SALL gene are necessary to keep the correct levels of its downstream targets." (PMID 22978642, 2012). "In human, mutation of SALL4 causes the development of acro-renal-ocular and Okihiro syndromes." (PMID 22848863, 2012). "Human SALL4 mutations are associated with the Duane-radial ray syndrome (DRRS, OMIM#126800, also known as Okihiro syndrome), which is a human autosomal-dominant syndrome involving multiple organ defects, including kidney malformation." (PMID 19440552, 2009). "We note that several of the highly correlated genes-SALL4 (Duane-Radial Ray Syndrome), PAX2 (Papillorenal syndrome), ACGT1 (Baraitser-Winter Syndrome 2), SALL1 (Townes-Brocks Syndrome 1) can also present with congenital renal anomalies." (PMID 40610405, 2025). "We note that several of the enriched genes-SALL4 (Duane-Radial Ray Syndrome), PAX2 (Papillorenal syndrome), ACGT1 (Baraitser-Winter Syndrome 2), SALL1 (Townes-Brocks Syndrome 1) can also present with congenital renal anomalies." (PMID 39606382, 2024). "In mouse, loss of SALL4 gene leads to embryonic lethality during implantation and heterozygous SALL4 mutant mouse recapitulate human Okihiro syndrome, an autosomal dominant disease with multiple developmental defects." (PMID 38062245, 2024). "Consistent with this discovery, thalidomide syndrome phenocopies Duane-radial ray syndrome (also called Okihiro syndrome; OMIM #607323), which is caused by mutations in SALL4." (PMID 37125615, 2023). "SALL4-related disorders include Duane-radial ray syndrome (DRRS, Okihiro syndrome) and acro-renal-ocular syndrome (AROS)." (PMID 23687435, 2013). "Mutations in the SALL4 gene have been shown to cause DRS and DRS-associated disorders, namely, Okihiro syndrome, acro-renal-ocular syndrome, Holt-Oram syndrome, or suspected thalidomide embryopathy." (PMID 23687435, 2013). "Okihiro syndrome is likely to result from Sall4 haploinsufficiency, because Sall4 heterozygous mice exhibit similar phenotypes to the human symptoms." (PMID 23825698, 2013). "Recently mutations of the sal-like 4 (SALL4; MIM# 607343) gene on chromosome 20 have been linked to DRS or DRS associated with radial forearm malformations, also known as Okihiro syndrome." (PMID 23687435, 2013).
Duane-radial ray syndrome (continued). "Holt-Oram syndrome and Duane-radial ray syndrome, which we discuss in Box 3, present similar phenotypes due to genetic perturbations in a shared molecular pathway: Tbx5 acts directly upstream of Sall4 during heart and appendage development in mice and in zebrafish." (PMID 37125615, 2023). "In zebrafish, SALL4 acts downstream of TBX5 and is required for pectoral fin outgrowth; mutations at the SALL4 locus on chromosome 20 resulted in a range of clinically overlapping phenotypes, including Okihiro syndrome, HOS, acro-renal-ocular syndrome, and thalidomide embryopathy." (PMID 36936432, 2023). "Moreover, in humans who possess SALL4 genetic variations, this leads to Duane-radial ray syndrome, in which there are limb and internal organ differences that can look remarkably similar to thalidomide embryopathy, and which has been confused with this condition." (PMID 37226469, 2023). "Some Okihiro syndrome patients have a presentation similar to thalidomide embryopathy; consistent with this, SALL4 is a cellular target of thalidomide, which facilitates binding of SALL4 to the CLR4CRBN E3 ubiquitin ligase that ubiquitylates SALL4 and leads to its destruction." (PMID 36635047, 2023). "Duane-radial ray syndrome (DRRS; MIM #607323) and Holt-Oram syndrome (HOS; MIM #142900) are both autosomal dominant conditions caused by mutations in SALL4 and TBX5 genes, respectively." (PMID 31388035, 2019). "When SALL4 heterozygotes were crossed with heterozygotes of SALL1, another SALL family member, the pups showed Okihiro syndrome-like phenotypes in the anorectal system, heart, brain, and/or kidneys, and did not survive long." (PMID 32414180, 2020). "To date, it has not been conclusively demonstrated that SALL4 is responsible for all the damage seen in thalidomide survivors and birth differences between thalidomide embryopathy and Duane-radial ray syndrome do differ." (PMID 37226469, 2023).